GAS5 (growth arrest specific 5)
Diseases named in the same sentence as GAS5 in open-access papers (continued):
Sharing a sentence is not in itself a finding about the gene and the disease.
mantle cell lymphoma (1 paper, 2021). Mantle cell lymphoma is a rare form of malignant non-Hodgkin lymphoma affecting B lymphocytes in the lymph nodes in a region called the ``mantle zone''. "Moreover, the expression of GAS5 is related to mTOR signaling pathway, which makes it a mediator of cytotoxic and cytostatic effects of rapalogues in mantle cell lymphomas." (PMID 35054253, 2021).
metastasis (1 paper, 2020). The spread or migration of cancer cells from one part of the body (where they first appeared) to another. "LncRNA GAS5 expression was not correlated with gender and age (p > 0.05) but with the Breslow’s thickness of the tumor, ulceration, lymph node metastasis, and tumor-node-metastasis (TNM) staging (p < 0.05)." (PMID 32308561, 2020).
monocytic leukemia (1 paper, 2021). "Another lncRNA, growth arrest-specific 5 (GAS5), localized in the nucleus of macrophages from the cell line THP-1 (a human monocytic leukemia cell line) and increased cellular apoptosis after their treatment with oxLDL." (PMID 34940525, 2021).
myelodysplastic syndrome (1 paper, 2023). A clonal hematopoietic disorder characterized by dysplasia and ineffective hematopoiesis in one or more of the hematopoietic cell lines. "The lncRNAs LOC101928834, H19, WT1-AS, TCL6, LEF1-AS1, EPB41L4A-AS1, PVT1, GAS5 and ZFAS were found to be relevant to myelodysplastic syndrome (MDS) pathogenesis and outcome." (PMID 36607351, 2023).
oral submucous fibrosis (1 paper, 2018). "GAS5 was also shown to inhibit myofibroblasts activity in oral submucous fibrosis." (PMID 30232236, 2018).
ovarian serous cystadenocarcinoma (1 paper, 2025). A malignant serous cystic epithelial neoplasm arising from the ovary. "Scatter plots show the correlations between FAM171A2 mRNA expression and six lncRNAs (BACE1-AS, GAS5, HOTAIR, HOXA10-AS, PVT1, and UCA1) in ovarian serous cystadenocarcinoma samples (n = 379) from the ENCORI database." (PMID 41303609, 2025).
panic disorder (1 paper, 2023). An anxiety disorder characterized by multiple unexpected panic attacks with persistent concern of recurring attacks. "Regarding panic disorder, data from our study indicates that the levels of DISC2, PANDA, HOTAIR, MALAT1 and GAS5 lncRNAs are over-expressed in the T1 patient group, while the T2 patients show similar levels to the controls." (PMID 37761918, 2023). "Further novelty concerns the gene expression levels of ncRNAs in Panic Disorder patients: from our observations, it was found that the ncRNAs DISC2, GAS5, HOTAIR, MALAT1, PANDA and miR-221-5p are significantly over-expressed in the T1 patients group compared with healthy controls." (PMID 37761918, 2023).
pituitary adenoma (1 paper, 2022). "Overall, these results demonstrated that lncRNA GAS5 inhibited proliferation, but promoted apoptosis of pituitary adenoma cells." (PMID 35435104, 2022).
psychosis (1 paper, 2018). "The expression levels of PINT and GAS5 decreased in participants with psychosis compared to control participants." (PMID 30567388, 2018). "In contrast we find reduced levels of GAS5 expression in psychosis." (PMID 30567388, 2018). "To advance our understanding of heterochromatin function in psychosis, and the modification of expression of lncRNAs with antipsychotics, we selected three lncRNA molecules as per the criterion noted: MEG3, PINT and GAS5." (PMID 30567388, 2018). "GAS5 is predictive of the control group characteristics and, we found that PINT has a predictive power (although not statistically significant) for the diagnosis of psychosis." (PMID 30567388, 2018).
rectal cancer (1 paper, 2022). A primary or metastatic malignant neoplasm that affects the rectum. "lncRNA GAS5 interacts with YAP1 phosphorylation and degradation to inhibit rectal cancer progression." (PMID 36299503, 2022).
serous ovarian cancer (1 paper, 2023). "GAS5 expression in serous ovarian cancer was significantly correlated with tumor pathological grade." (PMID 37639158, 2023).
Splenomegaly (1 paper, 2021). Abnormal increased size of the spleen. "The presence of constitutional symptoms was significantly associated with higher plasma levels of MALAT1 (p = 0.0302) or GAS5 (p = 0.0306), whereas splenomegaly was correlated to higher LINC01268 (p = 0.0012), MALAT1 (p < 0.0001) or GAS5 levels (p = 0.0006)." (PMID 34638230, 2021).
tauopathies (1 paper, 2025). "A previous study revealed GAS5 levels to be consistently reduced in human AD brain samples, and furthermore that depletion of GAS5 decreases insulin signaling in neurons and increases phosphorylated tau, which influences synaptic dysfunction in tauopathies." (PMID 39979805, 2025).
ulcers (1 paper, 2022). "The levels of GAS5 and miR-21 are significantly increased in CD4+ T cells of SLE patients, and GAS5 is expressed at a higher level in SLE patients with ulcers." (PMID 36325322, 2022).
Ureteral obstruction (1 paper, 2025). Obstruction of the flow of urine through the ureter. "During fibrotic remodeling, GAS5 constrains TGF-β signaling via the miR-142-5p axis, and loss of Gas5 worsens fibrosis after unilateral ureteral obstruction in mice." (PMID 41303683, 2025).
uveal melanoma (1 paper, 2023). A melanoma derived from melanocytes of the uveal tract. "Likewise, lncRNA GAS5 directly binds to miR-21 to suppress EMT in human uveal melanoma." (PMID 37229651, 2023).
tumor (482 papers, 2011 to 2026). "For GAS5 rs145204276, significant associations were observed between the del allele and advanced tumor stages (III + IV) (p = 0.015) as well as poorly differentiated tumors (G3) (p = 0.009)." (PMID 40243746, 2025). "In multiple cancers, GAS5 is a known tumor suppressor in which high levels are associated with increased apoptosis and decreased cell proliferation." (PMID 40331955, 2025). "Dysregulated expression of specific lncRNAs, including MRPL23-AS1, MALAT1 and GAS5, has been associated with tumor progression, poor prognosis and therapy resistance." (PMID 39895777, 2025). "GAS5, a long non-coding RNA encoded by the GAS5 gene, has recently been identified as a tumor suppressor in several types of cancer." (PMID 40799819, 2025). "Maximum intensity levels for GAS5 were associated with upper-end threshold levels for deep tumor necrotic zones." (PMID 38258133, 2024). "In the current study, we further explored the influence of tumor cell-derived GAS5 on immune cells in the TME and the underlying mechanism." (PMID 38762546, 2024). "Nevertheless, low transcript levels of the lncRNA GAS5 were noted in this location under similar conditions, reflective of its tumor suppressor status and association with overall GBM patient survival." (PMID 38258133, 2024). "GAS5 downregulation has been associated with altered cell cycle regulation and apoptosis, potentially contributing to tumor growth and survival." (PMID 38522008, 2024). "Such regions of tumor necrosis were associated with elevated lncRNA GAS5 expression in chemotherapeutic responsive patients, supporting its role as a tumor suppressor and prognostic biomolecule of extended overall survival." (PMID 38258133, 2024). "On the other hand, GAS5 functions in contrast as a tumor suppressor, with its downregulation in HCC linked to enhanced proliferation and reduced apoptosis." (PMID 39609501, 2024). "GAS5 is considered a tumour-suppressive lncRNA in association with many malignancies, in which the reduced expression of this transcript has been detected." (PMID 38790894, 2024). "It has been reported that elevated GAS5 is closely associated with cancer patients overall survival and acts as a functional tumor suppressor in the U87MG cell line." (PMID 38258133, 2024). "Previous reports have confirmed that low expression of GAS5 is associated with tumor recurrence, metastasis, low survival rate, and chemotherapy tolerance." (PMID 38782769, 2024). "A compelling example we identified is the host gene GAS5, which encodes a tumor-suppressor long noncoding RNA." (PMID 37072185, 2023). "GAS5 levels were found to be reduced in tumour specimens, which was associated with increased tumour dimensions, decreased differentiation, and more advanced stages of tumour-node metastasis." (PMID 38203731, 2023). "As GAS5 is associated with invasion, growth, tumor promotion, proliferation, and apoptosis of BC, metformin can regulate these features by GAS5 antitumor activity." (PMID 36849958, 2023). "Low GAS5 expression was significantly associated with low survival rate of GC and late Tumor Node Metastasis (TNM)." (PMID 37249580, 2023). "This suggests that in AML GAS5 has a tumor-suppressive function and it was also found that lower expression of GAS5 was associated with inferior outcome among younger AML-NK patients." (PMID 36362925, 2022). "Several studies have reported tumor suppressive roles of GAS5, and its reduction in malignant tumors is associated with an increase in malignancy, a poor prognosis, and drug resistance." (PMID 36672566, 2022). "GAS5 (Growth Arrest-Specific Transcript 5) is also an interesting tumour suppressor lncRNA whose lowered expression is associated with poorer clinical outcomes in a variety of human malignancies." (PMID 36230680, 2022). "Xenografted tumors in nude mice studies showed that GAS5 knockdown promoted tumor growth and caused worse lesions in colorectal." (PMID 36062165, 2022).
tumor (continued). "Regarding GAS5, the widely accepted function of GAS5 is that it is a tumor-suppressive lncRNA, which is implicated in a wide range of malignancies." (PMID 36310591, 2022). "In the present study, we demonstrated lncRNA GAS5 as a tumor suppressor suppressed proliferation of PitNET cells, and overexpressed GAS5 caused cell cycle arrest and apoptosis of PitNET cells." (PMID 35435104, 2022). "The possible explanation is that the alcohol-drinking patients have some genetic variations that influence the susceptibility of tumor progression or GAS5 expression." (PMID 33925911, 2021). "The expression level of GAS5 in TNBC patients was reported to associate with tumour resistance to several chemotherapeutic drugs, including adriamycin, paclitaxel and cisplatin." (PMID 33314471, 2021). "Our study demonstrates that female patients with UCC and carrying the Ins/Del or Del/Del genotype of GAS5 rs145204276 have a higher risk of larger tumor status." (PMID 32354045, 2020). "It has been also observed that the GAS5 were down regulated in Chinese Triple-negative breast cancer (TNBC) patients which was associated with tumor aggressiveness, lymph node metastasis, and survival." (PMID 31956395, 2020). "The data presented here demonstrate that carriers of the deletion allele of GAS5 rs145204276 are at a higher risk of larger tumor status than carriers of the wild type Ins/Ins genotype." (PMID 32354045, 2020). "A low expression of GAS5 characterized several different kind of tumor and was associated with poor prognosis in patients with thyroid cancer." (PMID 33114343, 2020). "Growth arrest–specific 5 (GAS5), a lncRNA, whose encoding takes place by the GAS5 gene, has been introduced as a tumor suppressor in variety of cancer types." (PMID 33569393, 2020). "Decreased GAS5 expression was associated with larger tumor size (≥5 cm), advanced clinical stage (III-IV), and poor prognosis of OvCa patients." (PMID 33238475, 2020). "Lastly, although Gas5 was discovered in mouse cells as a G0 gene, the evidence for the tumor suppressor role of mouse Gas5 (in Gas5 gain-of-function or loss-of-function experiments) is disappointing in scope." (PMID 31533355, 2019). "The panel of 21 lncRNA included GAS5 (growth arrest-specific 5), mapped at 1q25, a tumor suppressor-like associated with cell cycle arrest and apoptosis." (PMID 29389884, 2018). "GAS5 levels were significantly downregulated in BlCa and associated with invasive high-grade tumours, and high EORTC-risk NMIBC patients." (PMID 30374124, 2018). "GAS5 loss was correlated with unfavourable disease features, such as invasive disease stages and HG tumours, as well as high EORTC-risk group and positive FFC of the NMIBC (TaT1) patients." (PMID 30374124, 2018). "In this study, we show that GAS5 is under-expressed in three types of tumors, in addition to being associated with tumor prognosis in some types." (PMID 30289954, 2018). "In this study, in HCT-116 and HT-29 cells, we found that GAS5 significantly inhibit the release of IL-10 and VEGF-A, which indicates that GAS5 is involved in the tumour-associated inflammatory response." (PMID 28099146, 2017). "We observed that low GAS5 expression was associated with a larger tumor size and a poorer differentiation status." (PMID 25925741, 2015). "Although GAS5 has been suggested to have a tumor-suppressive role, the underlying mechanism of GAS5-mediated gene expression having an impact on tumorigenesis is still elusive." (PMID 24884417, 2014). "The downregulation of GAS5 is implicated in enhanced tumor aggressiveness." (PMID 41226688, 2025). "These variable expression patterns of GAS5 in different tumor types underline the context-dependent functionality, determined by the tumor microenvironment and complex regulatory networks like miRNA sponging, chromatin remodeling, and transcription factor binding." (PMID 39958058, 2025).
tumor (continued). "Further analysis of tumor site revealed a strong association between the GAS5 rs145204276 del allele and tumors located in the distal colon in the dominant model, with the relative risk for del carriers being 2.98 (95% CI: 1.57–5.66) compared to the more frequent ins/ins genotype." (PMID 40243746, 2025). "Therefore, in CC, lower GAS5 expression levels are linked to tumor progression and poorer clinical outcomes for individuals with CC." (PMID 38434620, 2024). "In this BC type, the expression of GAS5 was associated with tumor size, clinical stage, lymph node metastasis, and survival, suggesting that a high level of tissue GAS5 could favor a good clinical outcome for BC patients." (PMID 37444428, 2023). "The neutralization of IL-10 and VEGF-A reduced tumor proliferation caused by GAS5 knockdown." (PMID 37760852, 2023). "The results in xenografted tumors in nude mice showed that the knockdown of GAS5 could promote tumor growth and cause worse lesions in colorectal." (PMID 36062165, 2022). "This coincidence might indicate that the GAS5 SNP rs145204276 variants, especially the Del/Del variant, possess universal influences on tumor progression and angiogenesis-related disorders in Asian populations." (PMID 35456391, 2022). "Moreover, a study demonstrated that the progression of GC is driven by rs145204276 of GAS5, patients with allele del of rs145204276 located in the promoter region of GAS5, would result in a smaller tumor size and a lower risk of GC progression." (PMID 35837102, 2022). "GAS5 is implicated in human cancer as a tumor suppressor that is modulated by miRNAs." (PMID 36412908, 2022). "This relation of GAS5low status with adverse prognosis is consistent with studies investigating GAS5 in solid tumors, where decrease in GAS5 expression is associated with characteristics of advanced stage tumor, like tumor size and lymph node and distal metastases." (PMID 35054253, 2021). "GAS5 is a tumor suppressor gene located at chromosome 1q25.1 comprised of 12 exons non-encoding proteins, whose highly conserved introns encode an important lncRNA involved in carcinogenesis and tumor progression, marked as lncRNA GAS5." (PMID 33920083, 2021). "In addition to its potential suppressor role in tumor growth, GAS5 has also been shown to be associated with the response of several anticancer agents such as docetaxel, doxorubicin, and tamoxifen." (PMID 34094978, 2021). "Since down-regulation of GAS5 is a hallmark of different types of cancer, induction of GAS5 overexpression could aid in regression of the tumor." (PMID 35054253, 2021). "In ovarian cancer, loss of GAS5 is related to increased tumor volume and advanced tumor stage." (PMID 34527584, 2021). "The function of GAS5 may be affected by the genetic variants but still preserves tumor suppression function." (PMID 32547314, 2020). "Logistic regression models demonstrated that female patients with UCC carrying the rs145204276 GAS5 Ins/Del or Del/Del genotype had a 3.037-fold higher risk of larger tumor status (95% confidence interval 1.259–7.324) than did rs145204276 wild type (Ins/Ins) carriers (p = 0.011)." (PMID 32354045, 2020). "This low expression of exo-GAS5 was associated with larger tumor size and advanced TNM." (PMID 32438606, 2020). "Finally, they identified a significant association between lower Exo-GAS5 expression with larger tumor size and advanced TNM stage." (PMID 35582278, 2019). "Lower GAS5 expression in tumors was associated with a larger tumor size and advanced FIGO stage." (PMID 31382546, 2019). "Indeed, NMIBC patients underexpressing GAS5 were at significantly higher risk for disease short-term relapse and progression to invasive tumour stages." (PMID 30374124, 2018). "Gas5 expression was associated with tumor size and TNM staging." (PMID 29308053, 2018). "The AUC of 0.76 calculated for GAS5 in tumor diagnosis also suggests moderate diagnostic value." (PMID 29029523, 2017).